PALB2 (partner and localizer of BRCA2)
Diseases named in the same sentence as PALB2 in open-access papers (continued):
Sharing a sentence is not in itself a finding about the gene and the disease.
ovarian carcinoma (continued). "The coding region of the PALB2 gene was analyzed in 175 probands with family histories of breast and/or ovarian cancer ascertained from a single Canadian institution in Eastern Ontario." (PMID 25225577, 2014). "Germline mutations in at least four Fanconi Anemia genes (BRCA2, PALB2, RAD51C, BRIP1) have thus far been found to contribute to the inherited risk of breast or ovarian cancer." (PMID 24465539, 2014). "One PALB2 p.Q775X positive case was identified among the 491 women with ovarian cancer or low malignant potential tumors." (PMID 23302520, 2013). "Our findings and those of The Cancer Genome Atlas Research Network now challenge the contribution of PALB2 methylation to the dysfunction of the BRCA/FA pathway in this histological subtype of ovarian cancer." (PMID 23587053, 2013). "In the sporadic ovarian cancer samples, PALB2 methylation was reported to occur at a frequency of approximately 8%." (PMID 23587053, 2013). "As with BRCA2/FancD1, BRIP1/FancJ, and PALB2/FancN, bi-allelic mutations in RAD51C/FancO cause FA, and mono-allelic mutations increase the risk of breast and ovarian cancer." (PMID 23344037, 2013). "This is consistent with recent findings estimating that PALB2 heterozygotes were 1.3-fold more likely to have a relative with ovarian cancer in the context of HBOC family history." (PMID 23302520, 2013). "Another dysfunction of PALB2 detected in ovarian cancer was its expression silencing by promoter hypermethylation (in 4 of 53 sporadic cases)." (PMID 20122277, 2010). "In our study, there was a suspicion of LOH at PALB2 locus in one ovarian carcinoma with PALB2 deletion." (PMID 20122277, 2010). "The initial screening of 70 ovarian carcinomas revealed nine substitutions and one deletion of the PALB2 gene." (PMID 20122277, 2010). "In this study, we focused on GC-5′ss-exons of the breast and/or ovarian cancer (BOC) susceptibility genes, i.e., ATM (MIM#607585) exon 50, BRIP1 (MIM#605882) exon 1, and PALB2 (MIM#610355) exon 12, the last of which specifically undergoes skipping as a frequent alternative splicing event." (PMID 39518003, 2024). "Additionally, PALB2 hypermethylation has been reported in 8% of sporadic breast and ovarian cancer patients." (PMID 38898118, 2024). "In carriers of PALB2 PGV, risk is described as: (i) an absolute risk of BC ranging from 40 to 60%; (ii) a 10% absolute risk of contralateral BC; (iii) a 0.9% absolute risk of male BC; and (iv) an absolute risk of ovarian cancer ranging from 3 to 5%." (PMID 38672070, 2024). "We identified six cases harboring PALB2 PVs or LPVs among 918 breast and ovarian cancer patients." (PMID 37169825, 2023). "Although the relationship of ATM and PALB2 genes with ovarian cancer risk was not clear, RRSO was also performed in two patients considering personal and family histories." (PMID 37386498, 2023). "Mutations in other genes involved in DNA repair, such as PALB2, RAD51, and CHEK2 may be expressed in ovarian cancers." (PMID 37958970, 2023). "Interestingly, germline mutations in PALB2 and BARD1 and a high HRD score were identified in NETs, a rare tumor among malignant ovarian tumors." (PMID 35676859, 2023). "Women who test positive for an inherited pathogenic/likely pathogenic gene variant in BRCA1, BRCA2, PALB2, CHEK2 and ATM are at an increased risk of developing certain types of cancer—specifically breast (all) and epithelial ovarian cancer (only BRCA1, BRCA2, PALB2)." (PMID 35681696, 2022).
ovarian carcinoma (continued). "Pathogenic variants in PALB2, ATM and BARD1 are recognized by the NCCN as involved in hereditary breast and ovarian cancer syndrome but have insufficient evidence to determine their ovarian cancer risk." (PMID 35159349, 2022). "Mutations in BRCA1, BRCA2, RAD51C, and PALB2 genes were already shown to correlate with the risk of ovarian cancer, but not with BOTs." (PMID 35313928, 2022). "However, patient adherence rates across all patients and their relatives indicate that identifying P/LP variants in ATM, CHEK2, PALB2, and other DDR genes associated with increased risk of breast and ovarian cancer also impact patient care." (PMID 35626031, 2022). "In addition, BRCA1/2, ATM, BRIP1, PALB2, RAD51C, and RAD51D gene mutations are reported to be associated with high risk of ovarian cancers, and from the results of tumor tissue, it is easy to further determine their genetic status." (PMID 35186721, 2022). "Indeed, it has to be underlined that, beyond breast and ovarian cancers, pathogenic variants in BRCA1 and BRCA2, as well as in CHEK2 and PALB2, have been associated with a higher risk of developing an increasing number of cancers." (PMID 35456488, 2022). "Mutations in RAD51C, PALB2, and CHEK2 genes were previously analyzed in ovarian cancers." (PMID 33670479, 2021). "The detection of PALB2 and CHEK2 PGVs, in addition to PGVs detected in BRCA1/2, in breast/ovarian cancer is important for accurate risk assessment and the activation of subsequent cancer prevention and early detection strategies in the individual and their family." (PMID 34113003, 2021). "Despite some studies reported an association between PALB2 PVs and the diagnosis of ovarian cancer, to date evidence are not sufficient to support risk-reducing salpingo-oophorectomy." (PMID 33718150, 2021). "Along with BRCA1 (FANCS) and BRCA2 (FANCD1), involved in hereditary breast/ovarian cancer (HBOC) syndrome, three other members of the FANC family have been associated with an increased risk of development of BrCa and/or ovarian cancer (OvCa), namely BRIP1 (FANCJ), PALB2 (FANCN) and RAD51C (FANCO)." (PMID 29659569, 2018). "The prevalence and spectrum of recurrent PALB2 germline mutations in breast and ovarian cancer patients from Poland is not clearly defined." (PMID 28279176, 2017). "We also observed pathogenic mutations in several genes that have not traditionally been associated with increased risk of ovarian cancer (PALB2, ATM, and CHEK2)." (PMID 28281021, 2017). "Taking into account the well-established association of PALB2 with BC and its close relationship with BRCA1 and BRCA2, it is legitimate to inquire whether mutations in this gene would enhance the risk for ovarian cancer (OC)." (PMID 28858227, 2017). "Interestingly, one Fanconi anemia patient has been found to carry a homozygous truncating XRCC2 mutation while biallelic mutations in four breast and ovarian cancer susceptibility genes, BRCA2, BRIP1, PALB2, and RAD51C, are associated with Fanconi anemia." (PMID 25918678, 2015). "Nevertheless, PALB2 mutations and pathogenic mutations in other genes involved in the same pathway as BRCA2 could explain a minor part of the excess of pancreatic and ovarian cancer." (PMID 26082817, 2015).
ovarian carcinoma (continued). "Sixteen different FA genes have now been identified whose products act in a common pathway of DNA interstrand crosslink repair, and some of them (including BRCA2/FANCD1, BRIP1/FANCJ, PALB2/FANCN, and RAD51C/FANCO) have also been described as breast and ovarian cancer susceptibility genes." (PMID 24465539, 2014). "Our genetic analyses of the carrier ovarian cancer specimen harboring the PALB2 p.Q775X mutation did not exhibit evidence of LOH of the PALB2 locus." (PMID 23302520, 2013). "Genetic analysis of genomic DNA from ovarian cancer specimens did not indicate LOH of the PALB2 locus or identify a second mutation in the other coding exons of PALB2." (PMID 23302520, 2013). "Interestingly, all the four sporadic ovarian cancer cases that were found to be positive for PALB2 methylation in the Potapova study were clear cell carcinomas, or showed foci of clear cell carcinoma." (PMID 23587053, 2013). "Biallelic or in the case of FA-B hemizygous mutations in any one of the underlying genes lead to FA, while monoallelic mutations in FANCD1 (BRCA2), FANCJ (BRIP1), FANCN (PALB2) or FANCO (RAD51C) increase the risk of carriers for developing breast and ovarian cancer." (PMID 23285130, 2012). "One ovarian cancer patient with the PALB2 mutation had also a germline nonsense mutation of the BRCA2 gene." (PMID 20122277, 2010). "Here, we wanted to investigate whether large genomic rearrangements in PALB2 could also explain some of the Finnish breast and/or ovarian cancer families." (PMID 18501021, 2008). "The small number of PALB2 mutations limits interpretation; however, RAD51C, RAD51D, and BRIP1 mutations were associated with both high rates of biallelic loss and high GIS, suggesting that these genes might be true drivers of HRD in ovarian cancer." (PMID 39695768, 2024). "Therefore, the estimation of the contribution of CHEK2 and PALB2 pathogenic variants in hereditary breast and ovarian cancer risk is not possible based on the data presented herein, and is beyond the scope of this study." (PMID 35456488, 2022). "Moreover, it showed that germline PALB2 mutations were rare; PALB2 mutation carriers were found in only 0.21% of the ovarian cancer patients analysed, which is not significantly different from the frequency in the general population (0.05%)." (PMID 35805770, 2022). "In addition, it is well known that some HRR genes such as BRCA1/2, ATM, BRAD1, BRIP1, PALB2, RAD51C, and RAD51D are associated with high risk of ovarian cancers, and tissue detection might be a good way to learn the germline status." (PMID 35186721, 2022). "More recent studies have improved our understanding of inherited ovarian cancer risk beyond BRCA-related HBOC, and have allowed more detailed estimates of ovarian cancer risk for several homologous recombination (HR)-related genes with moderate-penetrance such as BRIP1, RAD51C/D, PALB2, and ATM." (PMID 35163487, 2022). "The ovarian cancer risk was associated with mutations in BRCA1 (OR = 40.79, 95% CI: 18.67–114.78; p = 0.29 × 10−15), in BRCA2 (OR = 25.98; 95% CI: 1.55–434.8; p = 0.001), in RAD51C (OR = 6.28; 95% CI 1.77–39.9; p = 0.02), and in PALB2 (OR 3.34; 95% CI: 1.06–14.68; p = 0.06)." (PMID 33670479, 2021). "BRCA1 and BRCA2 encode proteins involved in recombinational repair of damaged DNA and it has been found that mutations in other genes involved in the repair of DNA damage by homologous recombination, including e.g., RAD51C, RAD51D, BRIP1, PALB2, and CHEK2 may be associated with ovarian cancer risk." (PMID 33670479, 2021). "A study assessing CHEK2 and PALB2 mutations in high-risk Finnish BRCA1/2-founder mutation-negative breast and/or ovarian cancer individuals identified four cases of skin cancers with a co-occurring PALB2 and CHEK2 mutation, but unfortunately no details on the type of these cancers is included." (PMID 34084283, 2021).
ovarian carcinoma (continued). "Overall, significantly less ovarian cancer is seen in PALB2 families when compared with BRCA1 and BRCA2 families; therefore, it remains to be seen whether ovarian cancer risk is truly increased in individuals who are PALB2 mutation carriers or not." (PMID 26075229, 2015). "Thus, although it is likely that there is a moderately elevated risk for ovarian cancer associated with PALB2 mutations, the magnitude has not yet been established." (PMID 26484312, 2015). "We studied BRCA1/2 -negative breast and/or ovarian cancer families to a) assess the contribution of PALB2 mutations in this series and b) identify clinical, pathological and family history characteristics that might make PALB2 screening more efficient." (PMID 25225577, 2014). "In our study, PALB2 alterations did not associate with ovarian cancer risk." (PMID 20122277, 2010). "This study demonstrates that, among patients with breast or ovarian cancer, positive genetic test results in ATM, CHEK2, PALB2, and other DDR genes impact clinical recommendations for the majority of patients and/or their family members." (PMID 35626031, 2022). "In addition to the association between inherited ovarian cancer and RAD51, BRIP, and PALB2 pathogenic variants, MUTHY pathogenic variants confer an increased risk of ovarian cancer and may demonstrate resistance to platinum-based agents, much like tumours with mismatch repair deficiency." (PMID 36011309, 2022). "A total of 3,127 index cases with breast and/or ovarian cancer have undergone testing for PGVs of BRCA1, BRCA2, PALB2, and CHEK2_c.1100delC." (PMID 34113003, 2021). "At present, there is insufficient evidence to recommend risk-reducing ovarian surgery in the carriers of PALB2 variants, but, in the absence of a proven benefit of ovarian cancer screening, it could be considered in the post-menopausal setting, after non-directive counselling." (PMID 34771713, 2021). "In this single-center comprehensive study of germline PALB2 PGVs and the CHEK2_1100delC PGV in breast/ovarian cancer, we show a 1% detection rate for PALB2 PGVs, 1.4% for CHEK2_1100delC, and ~7% for BRCA1/2 PGVs." (PMID 34113003, 2021). "Importantly, mono-allelic mutations in certain FA genes including FANCD1 (BRCA2), FANCS (BRCA1), FANCN (PALB2), FANCM, FANCJ (BRIP1), and FANCO (RAD51C) that are believed to operate downstream in the pathway and implicated in HR are associated with sporadic breast and ovarian cancer." (PMID 30813363, 2019). "Another member of the BRCA/FA pathway, PALB2 (FANCN), was reported to have been inactivated by DNA methylation in some sporadic ovarian cancers." (PMID 23587053, 2013). "Initially, the entire coding sequence of the PALB2 gene with exon/intron boundaries was evaluated by the PCR-SSCP and direct sequencing methods on 70 ovarian carcinomas." (PMID 20122277, 2010). "This suggests that inactivation of the PALB2 gene may cause similar biological and phenotypic changes as inactivation of the BRCA1 or BRCA2 genes; the latter is responsible for a fraction of breast and ovarian cancers, and a dysfunction of BRCA2 alone - for the Fanconi anemia (FA) syndrome." (PMID 20122277, 2010). "In ovarian cancer, pathogenic variants in BRCA1, BRCA2, RAD51C, RAD51D, and PALB2 predict PARP inhibitor efficacy, but this has not been established for other HRR-related genes." (PMID 40069561, 2025).
ovarian carcinoma (continued). "Second, the ovarian cancer cohort is relatively small to draw a conclusion regarding the absence of PALB2 PV/LPV in ovarian cancer from this ethnicity." (PMID 37169825, 2023). "The real-world clinical impact of positive findings in ATM, CHEK2, PALB2, and other DDR genes conferring an increased risk of breast and/or ovarian cancer have not been well studied." (PMID 35626031, 2022). "In the course of our study, the ovarian cancer gene panel consisted of the five core genes (BRCA1, BRCA2, BRIP1, RAD51C and RAD51D), and it is likely that the gene panel will be expanded with other cancer genes, such as PALB2, in the near future." (PMID 34617209, 2022). "However, the indications for PARPi are broader for patients with other cancer types (e.g., prostate and ovarian cancer), involving additional biomarkers (e.g., ATM, PALB2, and CHEK) and genomic instability scores." (PMID 36077867, 2022). "The ovarian cancer risk was associated with mutations in BRCA1, BRCA2, RAD51C, and PALB2 but not in the CHEK2 gene." (PMID 33670479, 2021). "In our case-control analyses with a non-cancer east-Asian population and non-cancer females, we found significant prevalence of PALB2, BARD1, BLM, and ATM mutations in our HBOC cohort, including patients with ovarian cancer." (PMID 32566746, 2020). "The role that PALB2 plays in ovarian cancer chemoresistance has not yet been documented, although mutation has been associated with sensitivity to DNA damage in pancreatic tumours." (PMID 36046263, 2020). "The aim of the present study was to investigate the contribution of PALB2 germline mutations in a group of 460 BRCA1/2-mutation negative breast and/or ovarian cancer patients and identify the optimal panel of recurrent mutations for genetic screening of PALB2." (PMID 28279176, 2017). "We identified three pathogenic PALB2 mutations among 460 BRCA1/2-mutation negative breast and/or ovarian cancer patients." (PMID 28279176, 2017). "In summary, our study confirmed two PALB2 recurrent mutations, c.172_175delGA and c.509_510delGA, in BRCA1/2-mutation negative breast and/or ovarian cancer patients from Poland." (PMID 28279176, 2017). "We evaluated the frequencies of PALB2 germline mutations in 460 BRCA1/2-mutation negative breast and/or ovarian cancer patients." (PMID 28279176, 2017). "PALB2 mutation screening identifies a small, but significant number of mutations in BRCA1/2 -negative breast and/or ovarian cancer families." (PMID 25225577, 2014). "The entire coding sequence of the PALB2 gene was screened in 70 non-consecutive ovarian cancers only; the sensitivity of the SSCP ranges from 70% to 95%, according to different publications, and it is 90% in our laboratory." (PMID 20122277, 2010). "An analysis of the presence of mutations in BRCA1, BRCA2, RAD51C, PALB2, and CHEK2 with the age of onset of ovarian cancer revealed a lower age of ovarian cancer diagnosis in BRCA1 mutation carriers than in non-carriers of BRCA1 (51.6 vs. 57.6, p = 2.97 × 10−11)." (PMID 33670479, 2021). "Previous work suggested a similarly modest increase in risk for ATM and PALB2, but not for MRE11A13,14, casting doubt on whether the latter is truly an ovarian carcinoma predisposition gene." (PMID 32242007, 2020).